CXCL8 (C-X-C motif chemokine ligand 8)
Diseases named in the same sentence as CXCL8 in open-access papers (continued):
Sharing a sentence is not in itself a finding about the gene and the disease.
breast carcinoma (continued). "Recent studies showed that CXCL8 high expression serves as an unfavorable prognostic factor in most human cancers, such as breast cancer, colorectal cancer, melanoma, and lung cancer." (PMID 28883082, 2017). "CXCL8 has also been reported to promote the proliferation of human colon cancer, prostate cancer and breast cancer cells." (PMID 29285315, 2017). "Recent studies have revealed that CXCL8 is up-regulated and involved in the tumor progression of various human malignancies, including prostate cancer, breast cancer, gastric cancer, non-small lung cancer, colon cancer and melanoma." (PMID 29285315, 2017). "It has been revealed that CXCL8 promoted cell migration and/or invasion in human gastric cancer, colon cancer, breast cancer, hepatocellular carcinoma and prostate cancer in vitro." (PMID 29285315, 2017). "More importantly, TGF-β responsive gene ANGPTL4 and CXCL8 that are required for breast cancer lung metastasis and drug resistance were significantly inhibited by resveratrol." (PMID 28827661, 2017). "In several studies CXCL-8 has been shown to be a key player in the inflammatory/angiogenic microenvironment including increasing invasion and chemotaxis of breast cancer stem cells." (PMID 29387062, 2017). "For example ZO-1 which is required for the RhoA GEF ARHGEF11 and Cdc42 GEF Tuba to localize and function at TJ relocalizes from TJs in several breast cancer cell-lines and regulates CXCL8/IL-8 expression, a protein strongly implicated in tumour invasion." (PMID 25757376, 2015). "Populations of CSCs have been shown to express elevated levels of CXCR1 and the addition of CXCL8/IL-8 to epithelial breast cancer cells increased the number of CSCs." (PMID 26379707, 2015). "Upon activation by various stimuli, including IL-1β, NFκB transcriptionally regulates several genes involved in early inflammatory responses, such as the chemokine CXCL8, in a variety of cells, including breast cancer cells." (PMID 26696754, 2015). "Shao and colleagues demonstrated that silencing CXCL8 using siRNA in the MDA-MB-231 breast cancer cell line resulted in the upregulation of p27, downregulation of cyclin D1, and thus a delay in the progression from G1 to S phase." (PMID 25165728, 2014). "Besides, we measured an increased association between CXCL8 and expression of TNF itself in breast cancer cell lines (R2 = 0.34) versus all cell lines (R2 = 0.01)." (PMID 40833805, 2025). "Notably, nuclear factor of activated T cells 1 (NFAT1) in breast cancer cells transcriptionally upregulates CXC chemokine ligand 8 (CXCL8/IL-8) expression, driving localized neutrophil accumulation within tumors." (PMID 40568594, 2025). "Furthermore, we discovered that the expression of CXCL8 is highly correlated with that of CXCL1 transcripts in breast cancer cell lines." (PMID 40833805, 2025). "Importantly, the levels of CSCs, EMT-like mesenchymal phenotypes, as well as the expression of CXCL8 and PD-L1, are generally low in luminal A patients and breast cancer cells." (PMID 37190183, 2023). "Several scientific papers have also reported increased serum CXCL8 (p = 0.047; p < 0.001; p < 0.001) or plasma levels (p < 0.001; p = 0.005) in patients with early (p = 0.002) and advanced stages (p = 0.001) of breast cancer compared with healthy women." (PMID 37370728, 2023). "CXCL8 is also overexpressed in breast cancer and positively correlates with inflammatory cell activity, which may account for the aggressiveness of these tumors." (PMID 36431173, 2022). "Canertinib, an anti-neoplastic drug that could interact with CXCL8, had been demonstrated to be effective in inhibiting the growth of breast cancer cells." (PMID 36291687, 2022). "RelB/AhR complex is also involved in the overexpression of CXCL8 in breast cancer." (PMID 36588678, 2022).
breast carcinoma (continued). "Finally, the study of polymorphisms of inflammatory mediators such as the IL6, CXCL8, and TNF genes deserves attention because it can be helpful in the choice of the proper pain therapy for the postoperative period following breast cancer surgery." (PMID 34685397, 2021). "Moreover, EMT associated changes were connected to increased secretion of inflammatory soluble factors including CXCL8 from breast cancer cell lines." (PMID 33912188, 2021). "In breast cancer and pancreatic cancer patients, the expression of CXCL8 was higher in the tumor tissues; however, the OS time of patients who had a higher expression of CXCL8 was significantly shorter." (PMID 34439306, 2021). "CXCR1, one of the receptors for CXCL8, has been identified on breast cancer ALDH + CSC." (PMID 34476645, 2021). "CXCR1, one of the receptors for CXCL8, was identified on breast cancer (BC) CSCs." (PMID 31924241, 2020). "CXCL8 has the potential to be a prognostic marker for breast cancer and colorectal cancer." (PMID 32337262, 2020). "In keeping, breast cancer CSC were shown to proliferate in vitro in response to the addition of exogenous CXCL8 while a small molecular weight antagonist of CXCR1/2 (reparixin) or a blocking anti-CXCR1 (but not anti-CXCR2) monoclonal antibody were both able to deplete CSC in vitro." (PMID 30788286, 2019). "For example, in breast cancer, CXCL8 could facilitate tumorigenesis by modifying the microenvironment." (PMID 31304688, 2019). "A role for CXCL8 in bone metastatic disease was demonstrated in studies with breast cancer cells." (PMID 31572390, 2019). "Additionally, high levels of CXCL1, CXCL3, CXCL5, CXCL6, CXCL7 and CXCL8 are observed in drug-resistant breast cancer cells, which diminishes the effectiveness of other medical interventions." (PMID 31788042, 2019). "Polymorphisms in the CXCL8 and CXCR2 genes also suggest that elevated CXCL8 and CXCR2 expression may be risk factors of breast cancer." (PMID 31788042, 2019). "This suggests that the inactivation of ERα and upregulation of CXCL8 could promote angiogenesis in human breast cancer." (PMID 31788042, 2019). "In vitro experiments also showed that Rhus coriaria (a fruit displaying anticancer effects) dose dependently inhibits CXCL8 secretion in breast cancer cells; thus accounting, at least in part, for the inhibition of tumor growth and metastasis mediated by R. coriaria." (PMID 29977225, 2018). "High expression of CXCL8 was observed in several types of human cancer, such as lung cancer, breast cancer, colorectal cancer, prostate cancer, pancreatic cancer, hepatocellular carcinoma, head and neck squamous cell carcinoma, gastric cancer, leukemia, and melanoma." (PMID 28883082, 2017). "Since the increased level of CXCL8 in breast CSC have been shown to contribute to breast cancer aggressiveness by promoting VM46, it is reasonable that CXCL8 might contribute to BCL-XL increased VM formation, invasiveness, and stemness of both tumor types." (PMID 29238043, 2017). "IL-1β and TNF-α may alter stromal cells enhancing the expression of CCL2, CXCL8, and CCL5 by cancer-associated fibroblast and mesenchymal stem cells in the inflammatory tumor microenvironment of breast cancer." (PMID 27886105, 2016). "Also CXCL8 is overexpressed in invasive breast cancer cells and is believed to play a significant role in the progression of breast cancer." (PMID 26560478, 2015). "Importantly, CXCL8 plays a critical role in the increased migratory activity of different human breast carcinoma cell lines under oxygen deprivation." (PMID 26696754, 2015). "Interestingly, we previously reported that DACH1 attenuated Ras-induced migration, invasion and CXCL8 secretion in breast cancer." (PMID 25788272, 2015). "The outcome of such a process, if taking place in vivo in malignancies with high TNFα expression - as is the case in breast cancer - may be high production of pro-tumorigenic factors by the tumor cells, including angiogenic ones (such as CXCL8 and CCL2)." (PMID 24598028, 2014).
breast carcinoma (continued). "Increased expression levels of CXCL8 may also contribute to the multidrug resistance seen in human breast cancer cells." (PMID 23800251, 2013). "In addition to its secretion by tumor cells, CXCL8 has also been shown to be produced by monocytes when cultured with supernatants from freshly excised breast cancer tissue and mammary tumor cell lines." (PMID 23847541, 2013). "In breast cancer, CXCL8 expression level strongly correlated with activating transcription factor 3 (ATF3), c-Jun and JunB, members of the AP-1 transcription factor complex, and ATF3 and JunB were also observed to be upregulated in the metastatic osteosarcoma samples investigated here." (PMID 22518090, 2012). "TSA has previously been shown to up-regulate CXCL8 in lung and breast cancer cell lines." (PMID 21298036, 2011). "Finally, we tested whether CXCL8 and CXCL1 expressions correlate with EMT-associated genes, including VIM (gene for Vim), SNAI1 (gene for Snail1), and TWIST1 (gene for Twist1) in breast cancer cell lines using the HMS LINCS dataset." (PMID 40833805, 2025). "Finally, transcriptomic analysis of large datasets of cancer cell lines of different lineages, including breast cancer provided additional evidence of a lack of correlation between neutrophil guidance cues (CXCL8 and CXCL1) and EMT-associated genes." (PMID 40833805, 2025). "In addition, we also found that subunit p65 of NF-kappa(κ)B (NF-κB/p65), as a TF, could be phosphorylated by Kinectin 1, and these complex could activate the expression of chemokine CXCL8 in invasive basal-like breast cancer." (PMID 36814821, 2023). "Furthermore, four other candidate genes SPARC, THY1, IL1B and CXCL8 are reported in this study as the key regulatory genes which can modulate co-regulatory between different clusters in the PPI network of the brain metastasis tumours from breast cancers." (PMID 35045088, 2022). "CXCL8 secreted by tumor cells could enhance tumor progression by EMT in breast cancer cells." (PMID 35011369, 2021). "Recently, researchers have found that CXCL8 exerts multiple effects on biological activities of tumour cells including proliferation, invasion and migration, which are essential for tumour growth and metastasis, such as breast cancer, lung cancer, prostate cancer and colorectal carcinoma." (PMID 32588946, 2020). "For instance, interleukin-8 (IL-8/ CXCL8), a prototypical member of a superfamily of small, inducible secreted CXC chemokines, is positively associated with invasiveness and angiogenic and metastatic potential in breast cancer cells and is negatively linked to ER status." (PMID 33086721, 2020). "In this context, it is interesting to note that analysis of plasma from breast cancer patients identified significant correlation between increased CXCL8 levels and elevated degree of bone resorption as well as with bone metastasis, supporting key roles for CXCL8 in this setting." (PMID 32582148, 2020). "Finally, 6 genes (GOLGB1, TMEM158, CXCL8, MCM5, HIF1AN, and TSPAN31) were selected that could optimally predict the lung metastasis risk of breast cancer patients." (PMID 33378415, 2020). "Ginsenoside panaxatriol reduces the activation of NF-κB in breast cancer cells and thus decreases the expression of chemokines, such as CXCL1 and CXC motif chemokine ligand 8 (CXCL8)/interleukin-8 (IL-8), increasing the effectiveness of paclitaxel." (PMID 40427171, 2025). "In breast cancer, IL-17 has been shown to stimulate the production of several neutrophil-attracting chemokines, such as CXCL1, CXCL5, and CXCL8." (PMID 40486614, 2025). "First, we tracked CXCL8 and CXCL1 expressions across different breast cancer molecular subtypes using the HMS LINCS dataset." (PMID 40833805, 2025). "HBV infection lead to increased expression levels of several key genes in breast cancer cell lines, including CDK2, PCNA, CCNE2, CXCL8, E2F1, and CASP3." (PMID 40697521, 2025).
breast carcinoma (continued). "Recent studies have identified iCAF in several tumour types, including pancreatic cancer and breast cancer, using a variety of markers that encompass inflammatory cytokines and other genes (CXCL1, CXCL8, CXCL12, IL6, CFD, DPT)." (PMID 39757146, 2025). "For two pro-inflammatory proteins crucial in breast cancer metastasis and EMT process, IL6 and CXCL8, semi-quantitative results of the Human Profiler Cytokine Array Kit were verified by ELISA in a wider range of concentrations and incubation times." (PMID 40141419, 2025). "TNF-α stimulates the stromal cells and releases elevated levels of CCL2, CXCL8, and CCL5, which have tumor-promoting solid activities in general and breast cancer, mainly when derived from stroma cells." (PMID 38541912, 2024). "TAM-derived CXCL8 promotes breast cancer stem cell (BCSC) self-renewal and elevates breast cancer metastasis, and the CXCR2 antagonist danirixin inhibits the TAM/CXCL8 regulatory mechanism to eliminate BCSCs." (PMID 39199574, 2024). "Inhibition of the PI3K/AKT/mTOR axis has been shown to elicit senescence in breast cancer, resulting in the secretion of SASP factors (CCL2, CXCL1, CXCL8, IL‐6), which induce an M2‐like polarisation." (PMID 39270064, 2024). "Hub genes are involved in the generation of cancer stem cells (CSCs) and are related to inflammatory mediators, including CXCL8, IL1-β and PTGS2, which promote inflammation and breast cancer growth, metastasis, and development." (PMID 37138170, 2023). "Transcriptomic data from TEPA treated breast cancer cells also displays changes in the immune-related genes (including IL6, IL6R, IL15, CXCL1, CXCL8, and PTX3) in breast cancer." (PMID 37480151, 2023). "The binding of CXCL8 to its receptors CXCR1 and CXCR2 leads to the activation and downstream trafficking of inflammatory mediators, tumor proliferation and breast cancer development." (PMID 37065483, 2023). "CXCL8 plays a role in angiogenesis, and IL-1β enhances tumor inflammation, activates the β-catenin signaling pathway and induces EMT in breast cancer cells in addition to the expression of PTGS2." (PMID 37138170, 2023). "CXCL1, CXCL2, CXCL8, and CXCL12 were observed to diminish tumor response to chemotherapy, especially in breast cancers." (PMID 36612163, 2022). "CXCL1 and CXCL8 belong to the ELR-motif-containing group of CXC chemokines, which, in breast cancer (BC), stimulate angiogenesis and increase migration and invasiveness of tumor cells." (PMID 36431173, 2022). "Interleukin-8 (IL-8), also known as C-X-C motif ligand 8 (CXCL8), is a granulocytic chemokine with high expression levels in breast cancer." (PMID 35701840, 2022). "The CXCL8/CXCR2 axis plays important roles in the initiation and development of various cancers including CRC, breast cancer, prostate cancer, and lung cancer." (PMID 35898871, 2022). "Several previous studies have shown that CXCL8 which is a secreted protein functions with its receptors, CXCR1 and CXCR2, to promote the progression of some cancers, such as breast cancer, prostate cancer, lung cancer, and CRC." (PMID 35300114, 2022). "The gene-disease interaction network suggests the potential role of CXCL8, NOS2, and IL-6 in mediating mammary neoplasms, inflammation, hyperalgesia, cholestasis, and neoplastic cell transformation." (PMID 35720847, 2022). "Stromal cells such as CAFs and MSCs enhance the triple-negative subtype of breast cancer metastasis-related phenotypes, including angiogenesis, migratory, and invasive properties, by releasing inflammatory chemokines such as CCL2 and CXCL8." (PMID 35011369, 2021). "Out of 12 CXCL chemokines, we found that the expression of CXCL8, CXCL1, and CXCL2 transcripts was significantly elevated in ER- breast cancer specimens compared to ER+ samples in seven, four and three independent studies, respectively." (PMID 33912188, 2021).
breast carcinoma (continued). "MCF-7 breast cancer cells exposed to environmentally relevant concentrations of DDT exhibit upregulation of inflammatory and oxidative stress marker genes such as CXCL8, HMOX-1, and TNF." (PMID 35008370, 2021). "With respect to clinical relevance, a recent study indicated that CXCL8 neutralizing antibodies abrogated the ability of paclitaxel and gemcitabine to elevate CSC levels in breast cancer (tumor spheroids and ALDH-expressing cells)." (PMID 32582148, 2020). "Examples of this include, the bioactive lipid, lysophosphatidic acid, and its receptor, LPAR-1 in breast cancer, chemokines, CXCL8/IL8 and CXCR1 and CXCR2 in melanoma, pancreatic cancer and gastric tumors and CXCL12 and CXCR4 in multiple cancers." (PMID 33329395, 2020). "It has been recently proposed that a FOSL1 signature including TAN-attracting CKs (CXCL8, CXCL6 and CXCL5) is activated in Basal B type breast cancer cell lines." (PMID 31991796, 2020). "CXCR1, one of the receptors for CXCL8 (IL-8), was identified on ALDH+ breast cancer CSC, and the addition of recombinant CXCL8 increased the CSC population and its propensity for invasion." (PMID 31924241, 2020). "ELR+ CXC chemokines such as CXCL1 and CXCL8, as well as their CXCR1/CXCR2 receptors, have been demonstrated to be significant factors in promoting CSC enrichment in breast cancer." (PMID 32582148, 2020). "For example, CCL2, CCL5, CXCL8, and CXCL12 can promote breast cancer, while CXCL9, CXCL10, and CCL16 can inhibit breast cancer." (PMID 32253815, 2020). "CXCL8, a ligand for CXCR2, has been shown to regulate osteoclast activation both in a RANKL dependent and independent pathway during breast cancer bone metastasis." (PMID 30871004, 2019). "Another ligand, CXCL8, which binds to CXCR2 has been shown to influence bone metastasis in a RANKL-dependent and independent manner in breast cancer." (PMID 30871004, 2019). "Most of the reports in breast cancer bone metastasis evaluating chemokines CXCL6 and CXCL8 focus on CXCR1, expressed by osteoclasts." (PMID 30871004, 2019). "Reparixin is an allosteric inhibitor of IL-8 (CXCL8) receptor CXCR1/2 and has the activity against BCSCs in xenografts of breast cancer." (PMID 30175384, 2018). "Consistently, the significant positive correlations of CUL1 mRNA expressions with CXCL8 and IL11 mRNA expressions were observed in TCGA breast cancer dataset which includes 1153 breast cancer patients." (PMID 30578411, 2018). "The roles of CXCL8 and IL11 in CUL1-regulated breast cancer metastasis were further validated by CXCL8 and IL11 rescue assays." (PMID 30578411, 2018). "To confirm the role of CXCL8 and IL11 in CUL1 regulated breast cancer cell migration and angiogenesis, we performed CXCL8 and IL11 rescue assays." (PMID 30578411, 2018). "These chemokines are also known to regulate the expression of the pro-inflammatory cytokines MCP-1 (monocyte chemotactic protein-1; CCL2), IL-8 (CXCL8), and RANTES (CCL5) in breast cancer." (PMID 27515302, 2016). "In breast cancer, DACH1 has been shown to repress CXCL8 through blocking activation from AP1 and NF- kappaB binding sites and inhibit cyclin D1 transcription though AP-1/CREB." (PMID 25788272, 2015). "Overexpression of the IRX2 transcription factor in BT-549 and Hs578T breast cancer cells leads to concordant repression of CCL5, CXCL8 and CXCL10 mRNA expression." (PMID 26560478, 2015). "It has been reported that breast cancer stem cells express CXCR1, which upon binding of CXCL8 increase their activity (measured as sphere-formation) and self-renewal." (PMID 25165728, 2014). "EGF has also been found to induce the release of CXCL8 through signaling pathways involving Erk and PI3K in MCF-7 breast carcinoma cells." (PMID 23800251, 2013). "Interleukin-8 (IL-8/CXCL-8) is a prototype of the ELR+CXC chemokines that play an important role in the promotion and progression of many human cancers including breast cancer." (PMID 20540789, 2010).